RUNX1 (RUNX family transcription factor 1)
Diseases named in the same sentence as RUNX1 in open-access papers (continued):
Sharing a sentence is not in itself a finding about the gene and the disease.
cancer (continued). "Coculturing RUNX1-silenced HT29 cancer cells with IHH hepatocytes abolished the expression of ARP2/3 and vimentin in the hepatocytes." (PMID 35267627, 2022). "We revealed a prognostic correlation between RUNX1 expression and the infiltration of CAFs in various cancer types, according to most algorithms." (PMID 35534796, 2022). "These CRCLM specimens were generated previously with HT29 cancer cells expressing control or RUNX1 shRNA." (PMID 36330498, 2022). "Similar results were obtained when we cocultured hepatocytes directly with RUNX1-silenced HT29 cancer cells." (PMID 35267627, 2022). "We also observed a significant positive correlation between CAFs infiltration and RUNX1 expression in 32 types of human cancer based on all algorithms." (PMID 35534796, 2022). "We previously generated CRCLM lesions in SCID Beige mice using HT29 cancer cells expressing scrambled or RUNX1 shRNA." (PMID 36330498, 2022). "Dysregulation of RUNX1 expression contributes to the pathophysiology of IBMFS and cancer predisposition." (PMID 35765406, 2022). "Our results suggest that RUNX1 expression plays a detrimental role in four cancer types, including blood, brain, colorectal, and soft tissue cancers." (PMID 35534796, 2022). "Then we examined the effect of RUNX1 knockdown in the cancer cells on the co-cultured IHH hepatocytes." (PMID 36330498, 2022). "We searched the cBioPortal database to analyze the alteration frequency of the RUNX1 gene in different cancers based on TCGA pan-cancer analyses." (PMID 35534796, 2022). "An important regulator of vessel co-option in replacement HGP type of CRLM is a runt-related transcription factor-1 (RUNX1), which is upregulated in the cancer cells and associated with hepatocyte displacement and replacement by cancer cells." (PMID 36612177, 2022). "Subsequently, we queried the information of the genetic alterations of RUNX1 in the pan-cancer analysis, including the type, site, and case number of each genetic alteration, in the cBioPortal database." (PMID 35534796, 2022). "Our analysis indicated that RUNX1 had a detrimental effect on four cancer types, including blood, brain, colorectal, and soft tissue cancers." (PMID 35534796, 2022). "Next, we used the UALCAN database to explore the correlation between RUNX1 expression levels and promoter methylation in human cancers." (PMID 35534796, 2022). "To assess the prognostic role of RUNX1 in patients with cancer, we conducted a prognosis analysis across human cancers using PrognoScan and GEPIA." (PMID 35534796, 2022). "Of note, our previous publication had reported that the RUNX1-silenced cancer cells were less capable of generating liver metastasis, as well as forming vessel co-opting lesions compared to control cancer cells." (PMID 35267627, 2022). "Next, we used immunohistochemical (IHC) staining to further validate our results, which again demonstrated significant overexpression of RUNX1 in cancer cells of replacement lesions compared to desmoplastic." (PMID 34376784, 2021). "Firstly, we injected SCID Beige mice intrasplenically with HT29 cancer cells expressing scrambled or RUNX1 shRNA." (PMID 34376784, 2021). "We used recombinant TGFβ1 either individually or in combination with RUNX1 inhibitor (Ro5-3335) to treat the cancer cells for 24 h." (PMID 34376784, 2021). "In summary, these data suggest signaling crosstalk between hepatocytes and cancer cells that regulates the expression of both TGFβ1 and RUNX1, which is orchestrated through TSP1." (PMID 34376784, 2021). "According to the mRNA-seq results of the TCGA COAD dataset, RUNX1 was upregulated in COAD tissues compared with normal tissues, and the expression of RUNX1 increased to varying degrees in different histological types and cancer stages." (PMID 34659526, 2021). "TGFβ1-dependent ARP2/3 and vimentin expression in cancer cells were attenuated in the presence of RUNX1 inhibitor (Ro5-3335)." (PMID 34376784, 2021).
cancer (continued). "A dramatic increase in the ratio of desmoplastic lesions was detected in mice injected with RUNX1-depleted cancer cells comparing to controls." (PMID 34376784, 2021). "Taken together, these experiments indicate that TGFβ1 signaling can induce RUNX1 expression in cancer cells through TGFβRII." (PMID 34376784, 2021). "Additional putative targets of miR-129-5p that are associated with drug resistance in cancers are ABC transporters (ABCB1, ABCC5, ABCG1) and RUNX1." (PMID 34063443, 2021). "Here, we show that Runt Related Transcription Factor-1 (RUNX1) overexpression in the cancer cells of the replacement lesions drives cancer cell motility via ARP2/3 to achieve vessel co-option." (PMID 34376784, 2021). "The expression of CEBPG and RUNX1 proteins in the cancer tissues was significantly higher than that in the adjacent tissues (P < 0.05)." (PMID 32655621, 2020). "Runt-related transcription factor 1 (RUNX1) has been found as a key regulator in hematopoietic malignancies 11-13." (PMID 32549768, 2020). "TRAP staining showed that the RUNX1 T207D-overexpressing cancer cells-induced TRAP+ osteoclasts number was significantly increased compared with other cells." (PMID 32549768, 2020). "We found significant joint over expression of the JUN and FOS proto oncogenes in a cluster of cells for sample ETV6.RUNX1.2, suggesting deregulation in stress/cancer genes." (PMID 32415257, 2020). "Whilst the focus of RUNX1 research has therefore predominately been in the cancer field, accumulating evidence suggests that RUNX1 has more widespread functions in a range of organs and pathologies than previously considered." (PMID 32154891, 2020). "The association of RUNX1 mutations or changes in expression with the prognosis of patients has been reported in various carcinomas, and the effect of RUNX1 on prognosis varies considerably depending on the type of cancer." (PMID 32498288, 2020). "Immunoblotting showed that RUNX2 was expressed at a high level and RUNX1 at a variable level in 11 AGCT samples from the Alberta Cancer Research Biobank." (PMID 31311113, 2019). "Although much is known about the roles of CBFB and RUNX1 in the hematopoietic system and blood cancer, our knowledge of their functions and regulatory mechanisms in other tissues and cancers is very limited." (PMID 31061501, 2019). "It is worth noting that Runx1 has been previously reported to work in eye and cancer angiogenesis, cell-autonomously in the endothelial cells." (PMID 31343406, 2019). "Runt-related transcription factors (RUNX1–3) play an important role in normal tissue development and in cancer." (PMID 31311113, 2019). "RUNX1 is usually overexpressed in human cancers, and overexpression of RUNX1 is related to cancer progression and poor prognosis." (PMID 31015363, 2019). "Collectively, the most frequently mutated cancer myeloid genes were ASXL1 (47%), TET2 (37%), RUNX1 (27%) and SRSF2 (17%)." (PMID 30787430, 2019). "The actions of lncRNA-NEF in IHCC are likely achieved through the interactions with RUNX1, which is a well-characterized player in cancer biology." (PMID 31015363, 2019). "On the other hand, in less advanced carcinomas, we expected frequent RUNX1 expression and co-expression with PRMT1." (PMID 31655611, 2019). "A number of cancer-associated genes were found, including TGIF1, VEGFA, RUNX1, and PIM1, as well as others." (PMID 29641996, 2018). "We also included some genes from other pathways that affected patient survival time, such as Runx1 (pathway in cancer), Id3 (amino acid stimulus) and, Plaur (cytochrome c production)." (PMID 29434213, 2018). "This key finding shows that overexpression of Runx1 in mesenchymal cancer cells drives the cells back to the epithelial stage." (PMID 28407681, 2017). "Tumbar and the colleagues reported that transcriptional repression of SOCS3 and SOCS4 by RUNX1 were essential for cancer cell growth in oral, skin, and ovarian epithelial human cancer cells." (PMID 28750679, 2017).
cancer (continued). "Western blot of three paired cancers and matched adjacent normal tissues also showed a higher level of RUNX1 expression relative to normal pancreatic tissues." (PMID 29245924, 2017). "Our work shows by lost-of-function assays that Runx1 is able to modulate mammary gene expression towards a cancer behavior fate." (PMID 26735887, 2016). "In B cells infected by the cancer-associated Epstein-Barr virus (EBV), RUNX3 and RUNX1 transcription is manipulated to control cell growth." (PMID 26883634, 2016). "Altogether, our findings provide new insights into the potential of estrogenic GPER signalling to mediate cancer progression through the involvement of miR144 and Runx1 in both cancer cells and CAFs." (PMID 26030000, 2015). "In particular, the present data indicate the potential of GPER to modulate miR144 and Runx1 expression upon estrogen exposure towards cancer progression." (PMID 26030000, 2015). "Altogether, these results indicate that GPER mediates the regulation of miR144 and Runx1 by E2 and G-1 also in CAFs, which play relevant stimulatory effects through a functional interaction with cancer cells." (PMID 26030000, 2015). "However, in recent years, a new role for RUNX1 outside the haematopoietic system has started to emerge with several studies indicating how this transcription factor could be more broadly implicated in cancer." (PMID 24967588, 2014). "The invasive cancers showed different degrees of RUNX1 expression, predominantly localized to the nucleus." (PMID 24967588, 2014). "In the TN subgroup mean cancer-specific survival of RUNX1 positive patients was 129 months (95% CI, 114–144 months) compared to 163 months (95% CI, 148–179 months) of the RUNX1 negative group." (PMID 24967588, 2014). "Because RUNX1 is involved in blood cell development and certain cancers, this activity could be relevant to cancer biology." (PMID 41274412, 2025). "Expression of RUNX1 has been hypothesized to be protective to HR+ cancers as RUNX1 has an antagonistic effect on ERα signaling." (PMID 40614729, 2025). "In addition, we detected variants in several known cancer predisposition genes (eg, ETV6, RUNX1, ANKRD26, and IKZF1), highlighting the importance of long-term surveillance and genetic counseling in IPDs with potential malignant transformation risk." (PMID 40488176, 2025). "Four genes (DCC, EGFR, LRIG3, and RUNX1) mutated in GTKO-F0 pig No. 681 were previously found to be mutated in some human cancers." (PMID 40833781, 2025). "Among the RUNX family, RUNX1 exhibits a particularly complex role across different types of cancer." (PMID 38430423, 2024). "Thus, RUNX1 emerges as a complex regulator of angiogenesis, with both pro-angiogenic and anti-angiogenic roles varying by cancer type." (PMID 38430423, 2024). "Similarly, for INMON, FOXO3 and IRF5 were common TFs in healthy and early-stage tissues (e.g., BRCA1-mut); specifically, PRDM4 was the TF in precancer stages (e.g., Goiters and HT) while ATF2 and RUNX1 were enriched in cancers (e.g., ESCC and IDC)." (PMID 38645221, 2024). "RUNX1 showed up-regulated expression in a variety of cancers in pan-cancer analysis, and it may be a gene with broad oncogenic ability." (PMID 38886545, 2024). "KEGG analysis highlighted involvement in pathways such as ' signaling pathways regulating pluripotency of stem cells,' pathways in cancer,' ' mTOR signaling pathway,' ' GnRH signaling pathway,' and ' Wnt signaling pathway ', implicating RUNX1's role in tumorigenesis." (PMID 39309442, 2024). "The RUNX family, consisting of RUNX1, RUNX2, and RUNX3, has been recognized as crucial regulators in developmental processes, with dysregulation of these genes also being implicated in tumorigenesis and cancer progression." (PMID 39822248, 2024). "We selected RUNX1 for its well-studied role in cancer and as a master regulator of hematopoiesis, reasoning that mutations here could produce large detectable differences in gene expression." (PMID 38968069, 2024).
cancer (continued). "RUNX1 inhibition strategy is still at preclinical stage in cancer pathologies." (PMID 36766786, 2023). "Top expressed cancer-implicated gene targets for each TF converged on notable genes involved in cell signaling (SMAD3, PTPRJ), BCL6 regulation (FBXO11, BCOR), and transcriptional regulation (RUNX1, ERG, CUX1)." (PMID 38116118, 2023). "The contribution of Wnt signaling in EMT was also investigated in RUNX1 knockdown cancer cells." (PMID 38057816, 2023). "RUNX1 appears to be essential for solid tumor initiation and maintenance through upstream stimulation of STAT3 signaling, a central cancer pathway associated with a variety of cancer diseases." (PMID 37760803, 2023). "RUNX1 has been confirmed to act as an oncogene in a variety of cancers." (PMID 36982956, 2023). "RUNX1 plays an essential role in the regulation of apoptosis, suggesting the therapeutic potential of targeting RUNX1 in various diseases, especially cancer, and the development of novel RUNX1-based therapeutic approaches may be possible." (PMID 37760803, 2023). "Moreover, our IF staining showed that the expression of both cleaved caspase-3 and cleaved PARP-1 in hepatocytes appeared to be dependent on the presence of RUNX1 in the cocultured cancer cells." (PMID 35267627, 2022). "Importantly, upregulation of Ang1 in the hepatocytes is associated with the presence of runt-related transcription factor-1 (RUNX1) in the neighboring cancer cells in vitro and in vivo." (PMID 36330498, 2022). "In contrast, RUNX1 played a protective role in four other cancers." (PMID 35534796, 2022). "Therefore, we decided to examine the correlation between RUNX1 expression in the cancer cells and neutrophil infiltrates in CRCLM." (PMID 36330498, 2022). "To test our hypothesis, we generated HT29 cancer cells expressing either control shRNA or shRNA against RUNX1." (PMID 35267627, 2022). "Importantly, the knockdown of runt-related transcription factor 1 (RUNX1) in cancer cells attenuates the function of cancer cells in hepatocytes alterations in vitro and in vivo." (PMID 35267627, 2022). "Importantly, the expression levels of RUNX1 in the cancer cells were significantly correlated with the presence of neutrophils in the TME." (PMID 36330498, 2022). "Thus, we further verified RUNX1 protein expression in these cancers by immunohistochemistry, using the HPA database." (PMID 35534796, 2022). "Currently, it has been hypothesized that, due to the different expression level, the RUNX1 gene may play an oncogenic or suppressor role depending on the type of malignant tumor or hematological neoplasms." (PMID 36005134, 2022). "In light of these findings, we hypothesized that the presence of RUNX1 in cancer cells may also play a role in cancer cell-driven hepatocyte phenotype alterations." (PMID 35267627, 2022). "RUNX1 was found to be overexpressed in 14 cancer types and low expressed in one." (PMID 35522574, 2022). "Indeed, we observed a significant reduction of Ang1 in the liver parenchyma when the metastases were formed with cancer cells that RUNX1 knocked down." (PMID 36330498, 2022). "Interestingly, silencing RUNX1 in the cocultured cancer cells abrogated the cytotoxicity of cancer cells against hepatocytes." (PMID 35267627, 2022). "Furthermore, is there any potential for the development of new cancer therapies following recent findings regarding the role of RUNX1 in the malignant transformation ?" (PMID 35765406, 2022).
cancer (continued). "As previously reported, RUNX1 expression plays a dual role in different human cancers." (PMID 35534796, 2022). "Our results showed that RUNX1 overexpression may be a prognostic biomarker in several cancers, including CESC, COAD, GBM, and KIRC." (PMID 35534796, 2022). "To see the DNA binding consequences of cancer-associated missense mutations of RUNX1 and wild type RUNX1, we respectively explored Jurkat-cell RUNX1-ChIP-Seq (GSE17954) and LNCaP-cell RUNX1 Chip-Seq (GSM1527839), and used the homer motif of the RUNX1-ETS complex for the protein DNA model." (PMID 36090034, 2022). "Moreover, the upregulation of ARP2/3 in VCO-dependent cancer cells relies on runt-related transcription factor-1 (RUNX1), which is expressed upon the induction of transforming growth factor beta-1 (TGF-β1)." (PMID 36119528, 2022). "Importantly, our data suggested a new mechanism by which cancer cells promote neutrophil migration, which is mediated by the RUNX1-Ang1 pathway." (PMID 36330498, 2022). "Second, we studied the role of RUNX1 in human cancers using GEPIA." (PMID 35534796, 2022). "Globally, mouse models of RUNX1 overexpression do not lead directly to cancer by itself but increases cancer predisposition." (PMID 33743795, 2021). "However, we also observed significant upregulation of RUNX1 in the cancer cells of replacement HGP CRCLM lesions that are typically resistant to the combination of chemotherapy with bevacizumab (Chemo + bev)." (PMID 34376784, 2021). "TGFβ1 is among TGFβ members that modulate RUNX1 expression in cancer cells." (PMID 34376784, 2021). "We speculated that the expression of TGFβ1 in hepatocytes could be induced by secreted factors from the cancer cells, which are under the transcription control of RUNX1." (PMID 34376784, 2021). "Furthermore, overexpression of RUNX1 in the cancer cells is mediated by Transforming Growth Factor Beta-1 (TGFβ1) and thrombospondin 1 (TSP1)." (PMID 34376784, 2021). "Next, we asked whether RUNX1 expression in cancer cells was affected by the presence of TGFβ1 or TGFβRII in vitro." (PMID 34376784, 2021). "To further examine the molecular mechanisms explaining the signaling crosstalk between hepatocytes and cancer cells; we conducted a co-culturing experiment between hepatocytes and cancer cells followed by Western blotting to evaluate RUNX1 expression in the cancer cells." (PMID 34376784, 2021). "It is possible that overexpression of RUNX1 in these cancer types could also activate COL4A1 expression to promote tumorigenesis." (PMID 32746865, 2020). "Consequently, dysregulation or altered expression of RUNX1, which is well documented in cancer patients, leads to disrupted cellular function and disease." (PMID 32154891, 2020). "Runt-related transcription factor 1 (RUNX1) has many roles in cancer." (PMID 31739630, 2019). "Biological variables associated to a high risk of progression included CIP2A levels, the expression levels of the polycomb group BMI1 gene, the activation of beta-catenin, specific gene signatures, and mutations in cancer-associated genes such as ASXL1, IKZF1, RUNX1, SETD1B, GATA2, MLL, and UBE2A." (PMID 31709190, 2019). "A growing body of literatures has shown that RUNX1 is a key player in cancer biology." (PMID 31015363, 2019). "In addition, RUNX1 overexpression partially compensates the inhibitory effects of lncRNA-NEF overexpression on cancer cell migration and invasion (P<0.05)." (PMID 31015363, 2019). "As a consequence, the overall activity of RUNX1 in the cancer cells is decreased." (PMID 31048839, 2019).